RNGTT (RNA guanylyltransferase and 5'-phosphatase)
Description:
Bifunctional mRNA-capping enzyme exhibiting RNA 5'-triphosphate monophosphatase activity in the N-terminal part and mRNA guanylyltransferase activity in the C-terminal part. Catalyzes the first two steps of cap formation: by removing the gamma-phosphate from the 5'-triphosphate end of nascent mRNA to yield a diphosphate end, and by transferring the GMP moiety of GTP to the 5'-diphosphate terminus of RNA via a covalent enzyme-GMP reaction intermediate.
Synonyms: CAP1A; HCE; HCE1; hCAP
Tractability: Small molecule: a structure with a bound ligand is known; it has a high-quality binding pocket. PROTAC: ubiquitination databases record sites on it; its protein half-life has been measured.
Target class: Enzyme; Transferase
Gene: Protein-coding gene on chromosome 6 (88,609,897 to 88,963,626, reverse strand). Ensembl gene ENSG00000111880.
Subcellular location: Nucleus
Subcellular location (Human Protein Atlas): Nucleoplasm
Pathways (Reactome):
Disease: RNA Pol II CTD phosphorylation and interaction with CE during HIV infection
Gene expression (Transcription): RNA Pol II CTD phosphorylation and interaction with CE
Metabolism of RNA: mRNA Capping
Gene Ontology:
Molecular function: inorganic triphosphate phosphatase activity; mRNA guanylyltransferase activity; protein binding; RNA guanylyltransferase activity; polynucleotide 5'-phosphatase activity; ATP binding; catalytic activity; mRNA 5'-triphosphate monophosphatase activity
Biological process: 7-methylguanosine mRNA capping; RNA processing
Cellular component: nucleoplasm; nucleus
Genetic constraint (gnomAD): Loss-of-function variants: 15 observed, 41.1 expected, observed/expected ratio (o/e) 0.36, 90% interval 0.24 to 0.56. The upper end of that interval is the gene's LOEUF score, 0.56, which puts it in group 2 of 6, group 1 being the genes least tolerant of losing a copy. Missense variants: 329 observed, 466.67 expected, observed/expected ratio (o/e) 0.7, 90% interval 0.64 to 0.77. Synonymous variants: 155 observed, 155.85 expected, observed/expected ratio (o/e) 0.99, 90% interval 0.87 to 1.14.
Homologues: Orthologues: chimpanzee RNGTT (100% identical), macaque RNGTT (99% identical), pig RNGTT (98% identical), rabbit RNGTT (97% identical), mouse Rngtt (95% identical), rat Rngtt (95% identical), guinea pig RNGTT (92% identical), dog RNGTT (88% identical), tropical clawed frog rngtt (82% identical), zebrafish rngtt (78% identical), Drosophila melanogaster mRNA-cap (50% identical), Caenorhabditis elegans cel-1 (41% identical). Paralogues in human: DUSP11 (15% identical).
Diseases named in the same sentence as RNGTT in open-access papers:
RNGTT is named in the same sentence as 13 diseases in open-access papers, as found by Europe PMC text mining. Sharing a sentence is not in itself a finding about the gene and the disease. The quoted sentences say what the papers report.
acute myeloid leukemia (1 paper, 2025). Acute myeloid leukemia (AML) is a group of neoplasms arising from precursor cells committed to the myeloid cell-line differentiation. "Eukaryotic translation initiation factor 4E (eIF4E), a prooncogenic protein increased in acute myeloid leukemia (AML), specifically binds to m7 G caps and stimulates the export and translation of RNMT and RNGTT." (PMID 40483535, 2025).
renal cell carcinoma (1 paper, 2025). "Similarly, ENPP3 promotes cell-intrinsic growth and migration of renal cell carcinoma cells, but also regulates the availability of STING ligands for immune cells, and given its central role in RNA capping, RNGTT has the potential to affect many other genes with indirect effects on tumour growth." (PMID 40336011, 2025).
cancer (3 papers, 2013 to 2026). A tumor composed of atypical neoplastic, often pleomorphic cells that invade other tissues. "Accordingly, RNGTT is a common essential gene, required for growth of virtually all cancer cell lines, and its direct pro-tumour activity is associated with worse prognosis on most cancer types." (PMID 40336011, 2025).
tumour (1 paper, 2025). "Consistent with their transcriptional profile and the pro-tumour activities of RNGTT, HERVE 6q15−/− 2D11 cells exhibited increased in vitro growth, altered morphology and increased migration." (PMID 40336011, 2025).
RNGTT also shares sentences with these, for which no sentence is quoted: infection (3 papers); viral infection (2); breast carcinoma (1); dengue (1); Ebola (1); epilepsy (1); measles (1); nevus (1); ZIKV infection (1).